ERCC8 (ERCC excision repair 8, CSA ubiquitin ligase complex subunit)
Description:
Substrate-recognition component of the CSA complex, a DCX (DDB1-CUL4-X-box) E3 ubiquitin-protein ligase complex, involved in transcription-coupled nucleotide excision repair (TC-NER), a process during which RNA polymerase II-blocking lesions are rapidly removed from the transcribed strand of active genes. Following recruitment to lesion-stalled RNA polymerase II (Pol II), the CSA complex mediates ubiquitination of Pol II subunit POLR2A/RPB1 at 'Lys-1268', a critical TC-NER checkpoint, governing RNA Pol II stability and initiating DNA damage excision by TFIIH recruitment. The CSA complex also promotes the ubiquitination and subsequent proteasomal degradation of ERCC6/CSB in a UV-dependent manner; ERCC6 degradation is essential for the recovery of RNA synthesis after transcription-coupled repair. Also plays a role in DNA double-strand breaks (DSSBs) repair by non-homologous end joining (NHEJ).
Synonyms: CKN1; CSA; UVSS2
Tractability: Small molecule: a structure with a bound ligand is known. PROTAC: ubiquitination databases record sites on it.
Gene: Protein-coding gene on chromosome 5 (60,866,454 to 60,945,073, reverse strand). Ensembl gene ENSG00000049167.
Subcellular location: Nucleus; Chromosome; Nucleus matrix
Subcellular location (Human Protein Atlas): Nuclear speckles
Pathways (Reactome):
DNA Repair: Dual incision in TC-NER; Formation of TC-NER Pre-Incision Complex; Gap-filling DNA repair synthesis and ligation in TC-NER; Transcription-Coupled Nucleotide Excision Repair (TC-NER)
Metabolism of proteins: Neddylation
Gene Ontology:
Molecular function: protein binding; ubiquitin-like ligase-substrate adaptor activity
Biological process: DNA damage response; double-strand break repair via classical nonhomologous end joining; proteasome-mediated ubiquitin-dependent protein catabolic process; protein autoubiquitination; protein polyubiquitination; protein ubiquitination; regulation of transcription-coupled nucleotide-excision repair; response to oxidative stress; response to UV; single strand break repair; transcription-coupled nucleotide-excision repair; nucleotide-excision repair; response to auditory stimulus
Cellular component: chromosome; Cul4-RING E3 ubiquitin ligase complex; Cul4A-RING E3 ubiquitin ligase complex; nuclear matrix; nucleotide-excision repair complex; nucleus; protein-containing complex; site of DNA damage; Cul4B-RING E3 ubiquitin ligase complex; nucleoplasm; perikaryon
Genetic constraint (gnomAD): Loss-of-function variants: 28 observed, 23.82 expected, observed/expected ratio (o/e) 1.18, 90% interval 0.87 to 1.61. The upper end of that interval is the gene's LOEUF score, 1.61, which puts it in group 6 of 6, group 1 being the genes least tolerant of losing a copy. Missense variants: 270 observed, 241.81 expected, observed/expected ratio (o/e) 1.12, 90% interval 1.01 to 1.24. Synonymous variants: 82 observed, 84.08 expected, observed/expected ratio (o/e) 0.98, 90% interval 0.81 to 1.17.
Gene-disease validity (ClinGen):
ClinGen rates the evidence that ERCC8 causes each of these diseases.
Cockayne syndrome type 1 (autosomal recessive): Definitive.
Homologues: Orthologues: chimpanzee ERCC8 (100% identical), rabbit ERCC8 (95% identical), rat Ercc8 (91% identical), mouse Ercc8 (90% identical), dog ERCC8 (90% identical), pig ERCC8 (89% identical), macaque ERCC8 (88% identical), tropical clawed frog ercc8 (76% identical), zebrafish ercc8 (73% identical), Caenorhabditis elegans csa-1 (17% identical). Paralogues in human: GRWD1 (20% identical), GEMIN5 (18% identical), WDR59 (17% identical), RBBP7 (14% identical), RBBP4 (14% identical), PEX7 (12% identical), WDR24 (11% identical), WDR73 (11% identical), WDR77 (9% identical).
Diseases named in the same sentence as ERCC8 in open-access papers:
ERCC8 is named in the same sentence as 46 diseases in open-access papers, as found by Europe PMC text mining. Sharing a sentence is not in itself a finding about the gene and the disease. The quoted sentences say what the papers report.
Cockayne syndrome (42 papers, 2014 to 2026). A multisystem condition characterized by short stature, a characteristic facial appearance, premature aging, photosensitivity, progressive neurological dysfunction, and intellectual deficit. "Other mutations that lead to Cockayne syndrome occur in the ERCC8 gene that encodes the CSA protein and, most rarely, genes that encode components of the TFIIH transcription factor complex." (PMID 39996712, 2025). "Cockayne Syndrome (CS) is a rare autosomal recessive genetic disease, mainly caused by ERCC8 and ERCC6 gene defect." (PMID 41299792, 2025). "Mutations in the ERCC6 and ERCC8 genes are the predominant causes of Cockayne syndrome, with ERCC6 gene mutations present in approximately 75% of cases." (PMID 39473441, 2024). "Cockayne syndrome (CS), is an autosomal recessive condition caused by mutations in either ERCC8 (20% of cases) or ERCC6 (80% of cases) genes, encoding for CSA and CSB proteins, respectively." (PMID 39209536, 2024). "A notable example is ERCC8, involved in DNA damage repair and when mutated causes Cockayne Syndrome, an early-onset degenerative condition." (PMID 38872308, 2024). "Homozygous or compound heterozygous pathogenic variants in the ERCC8 gene have been associated with Cockayne syndrome type A (OMIM 216400)." (PMID 40225944, 2024). "Previous studies have identified homozygous mutations in ERCC8 as causal for Cockayne Syndrome type A (CSA), a UV light-sensitive syndrome, and several ARCAs." (PMID 36231052, 2022). "The dysfunction of ERCC8 has previously been linked with Cockayne syndrome (CS) and a UV-light sensitive syndrome (UVSS)." (PMID 36231052, 2022). "A novel splice site variant found in the Cockayne syndrome group A gene (ERCC8: c.551-1G>A) was associated with HI in two Somali siblings." (PMID 34609590, 2022). "In the present work we report the largest cohort of patients with Cockayne syndrome due to ERCC8/CSA mutations in Tunisia and North Africa, and enlarged the description of ERCC8/CSA variants globally." (PMID 35248096, 2022). "Cockayne Syndrome is due to mutations in the CSA (Ercc8) or CSB (Ercc6) genes involved in the first steps of transcription-coupled repair (TC-NER)." (PMID 34102225, 2021). "Cockayne syndrome is a neurodegenerative disease caused by the mutation in either Cockayne syndrome A (CSA/ERCC8) or Cockayne syndrome B (CSB/ERCC6) genes, which leads to impaired transcription-coupled NER." (PMID 32605254, 2020). "There are three exceptions in the database: one is the p.T322X mutation in the ERCC8 gene causing Cockayne syndrome that was shown to be frequent in the entire Christian Arab community and has been reported in Christian Arabs from Lebanon." (PMID 28302154, 2017). "Mutations in the ERCC6 and ERCC8 genes are known to cause Cockayne syndrome and approximately 65% individuals with CS have mutations in the ERCC6 gene." (PMID 25463447, 2014). "Mutations of the ERCC6 and ERCC8 genes are the predominant cause of Cockayne syndrome, and the ERCC6 gene mutation is present in approximately 65% of cases." (PMID 25463447, 2014). "Loss of ERCC8 will have insulin-dependent diabetes with Cockayne syndrome." (PMID 37293508, 2023). "Cockayne syndrome (CS) is a rare progeroid disorder characterized by growth failure, microcephaly, photosensitivity, and premature aging, mainly arising from biallelic ERCC8 (CS-A) or ERCC6 (CS-B) variants." (PMID 35748794, 2022). "Cockayne syndrome (CS) is a rare disease caused by mutations in ERCC6/CSB or ERCC8/CSA." (PMID 34946871, 2021). "Cockayne Syndrome is an autosomal recessive disorder that arises from mutations in one of two distinct genes: (i) excision repair cross‐complementing protein group 6 (ERCC6/CSB) or excision repair cross‐complementing protein group 8 (ERCC8/CSA), located in chromosomes 10q11 and 5q11, respectively." (PMID 40536083, 2025). "Using “Cockayne Syndrome” and “ERCC8” as keywords, we retrieved 25 articles from 2020 to 2024, encompassing 33 cases." (PMID 41299792, 2025).
Cockayne syndrome (continued). "Cockayne Syndrome (CS) is an autosomal recessive disorder arising from mutations in either of two disease‐associated genes, ERCC6 or ERCC8." (PMID 40536083, 2025). "Cockayne syndrome (CS), a rare hereditary neurodegenerative disorder caused by pathogenic variants in ERCC6 (CSB) and ERCC8 (CSA), often clinically overlaps with cerebral palsy (CP), leading to misdiagnosis." (PMID 40842628, 2025). "The loss-of-function mutations in ERCC8 and ERCC6 genes occurring in Cockayne syndrome patients prevent the removal of these bulky DNA lesions by TC-NER." (PMID 39209536, 2024). "ERCC8 encodes DNA excision repair complementation (ERC) proteins, and when mutated, causes the Cockayne syndrome." (PMID 38890712, 2024). "CS is caused by mutations in the ERCC6 and ERCC8 genes coding for Cockayne Syndrome group B protein (CSB) (accounting for 80% of cases) and Cockayne Syndrome group A protein (CSA) (accounting for approximately 20% of the cases), respectively." (PMID 36979413, 2023). "It is caused by mutations in either the ERCC6 or ERCC8 genes, encoding CSB or the Cockayne Syndrome A (CSA) protein, respectively." (PMID 28292928, 2017). "Cockayne Syndrome is a genetically heterogeneous disorder partially overlapping with Xeroderma Pigmentosum caused by biallelic mutations in genes regulating DNA repair (ERCC6, ERCC8)." (PMID 36862146, 2023). "Despite this fitting phenotype, the diagnosis “Cockayne syndrome” was only made after the identification of biallelic ERCC8 variants, mainly due to the lack of photosensitivity." (PMID 35748794, 2022). "Cockayne Syndrome (CS) has three subtypes: caused by mutations in either ERCC6 (CSB), ERCC8 (CSA), and an as-yet unknown third gene." (PMID 35812759, 2022). "A major challenge in this field is that mutations of the Cockayne syndrome‐associated genes, ERCC8 and ERCC6, do not recapitulate features of the human disorder in mice." (PMID 35834102, 2022). "Cockayne syndrome is divided into two categories by the mutations in the ERCC6 and ERCC8 genes." (PMID 34833108, 2021). "In addition, hypomyelination was characterized in Cockayne syndrome, another disorder with ERCC6 and ERCC8 mutations also causing defective DNA repair after UV damage." (PMID 29451896, 2018).
breast carcinoma (4 papers, 2015 to 2023). "The findings from our analyses of transcriptome and TCGA datasets further suggest a potential main or modifying effect for ERCC8 in breast cancer susceptibility." (PMID 33277540, 2020). "The mutation frequency of ERCC8 (0.3%) in breast tumors was also similar to some of the other known breast cancer susceptibility genes such as STK11 (0.3%) and LSP1 (0.3%)." (PMID 33277540, 2020). "Integrative genomics approach suggests that ERCC6 may be a previously unreported low- to moderate-risk breast cancer susceptibility gene, which may also interact with ERCC8." (PMID 38091511, 2022). "Joint effect analysis revealed increased risk of breast cancer with the ERCC8 1/1 and ERCC6 2/5 diplotype combination (OR 3.03, 95% CI 1.16–7.91, p = 0.024) and the ERCC8 1/1 and ERCC6 1/6 diplotype combination (OR 3.27, 95% CI 1.17, 9.18, p = 0.024) compared with the reference category." (PMID 33277540, 2020). "Using a hypothesis-driven (candidate-gene) integrative genetic epidemiologic approach to analysis of raw multi-omics data, we tested the association of ERCC6 and ERCC8 with peri- and post-menopausal breast cancer." (PMID 33277540, 2020). "We found significant upregulation of ERCC6 (p = 7.95 × 10–6) and ERCC8 (p = 4.67 × 10–6) in breast cancer and similar frequencies of ERCC6 (1.8%) and ERCC8 (0.3%) mutations in breast tumors to known breast cancer susceptibility genes such as BLM (1.9%) and LSP1 (0.3%)." (PMID 33277540, 2020). "Our integrative genomics approach suggests that ERCC6 may be a previously unreported low- to moderate-risk breast cancer susceptibility gene, which may also interact with ERCC8." (PMID 33277540, 2020). "It indicates that the doxorubicin induces the dysregulation of hiPSC-CMs derived RAD9A, HSPA1B, GATA2, IGF2R, CD200, ERCC8, and BCL11A genes that are associated with the pathogenesis of doxorubicin-induced cardiotoxicity in breast cancer patients." (PMID 37684436, 2023). "We report on the analysis of raw multiomics data from several relevant GWAS, transcriptome, and somatic mutation datasets to test the association of breast cancer with two candidate genes, ERCC6 and ERCC8." (PMID 33277540, 2020). "Analysis of TCGA breast tumors also revealed a higher mutation frequency for all known breast cancer susceptibility genes and for ERCC6 and ERCC8 compared to the average for all other genes." (PMID 33277540, 2020). "Joint effect analysis revealed increased risk of breast cancer with the ERCC8 0/0 and ERCC6 2/4 diplotype combination (OR 5.31, 95% CI 1.22–23.09, p = 0.026) and the ERCC8 0/5 and ERCC6 0/0 diplotype combination (OR 5.09, 95% CI 1.23, 21.03, p = 0.025) compared with the reference category." (PMID 33277540, 2020). "Our candidate-gene association analyses of GWAS datasets suggested an increased risk of breast cancer with ERCC6 (main effect: 1.29 ≤ OR ≤ 2.91, 0.005 ≤ p ≤ 0.04, 11.8 ≤ MAF ≤ 40.9%), and implicated its interaction with ERCC8 (joint effect: 3.03 ≤ OR ≤ 5.31, 0.01 ≤ pinteraction ≤ 0.03)." (PMID 33277540, 2020). "None of ERCC8 SNPs, haplotypes or diplotypes were associated with a statistically-significant increased risk of breast cancer." (PMID 33277540, 2020). "This analysis revealed that high-penetrance breast cancer susceptibility genes had higher mutation frequencies than medium- and low-penetrance genes, which had similar mutation frequencies to each other and to ERCC6 and ERCC8." (PMID 33277540, 2020). "None of the ERCC8 SNPs, haplotypes or diplotypes were associated with a statistically significant increased risk of breast cancer in CGEMS." (PMID 33277540, 2020). "None of the ERCC8 SNPs, haplotypes or diplotypes were associated with an increased risk of breast cancer at a statistically-significant level." (PMID 33277540, 2020).
breast carcinoma (continued). "Finally, we validated the expression level of immune-related genes in breast cancer patients-derived cardiomyocytes with doxorubicin-induced cardiotoxicity and found that the level of RAD9A, HSPA1B, GATA2, IGF2R, CD200, ERCC8, and BCL11A genes are consistently dysregulated." (PMID 37684436, 2023). "Finally, we validated that RAD9A, HSPA1B, GATA2, IGF2R, CD200, ERCC8, and BCL11A genes are consistently dysregulated in the doxorubicin-induced human-induced pluripotent stem cell-derived cardiomyocytes (hiPSC-CMs) derived from breast cancer patients." (PMID 37684436, 2023). "Conversely, some of the detected regions in the present work are not strongly related to breast cancer; recurrent losses affecting 7p22 (segment encompassing, among others, the PMS2 gene) and 5q11-q13 (ERCC8 and XRCC4) could suggest the involvement of DNA repair pathways in cancer progression." (PMID 25391423, 2015).
Cockayne Syndrome A (4 papers, 2014 to 2022). "This event calls into action numerous factors, including the TFIIH complex, XPA, RPA, and the TC-NER proteins, Cockayne syndrome A (CSA, a.k.a., ERCC8), and CSB (a.k.a., ERCC6)." (PMID 35456958, 2022). "RNA polymerase II stalls at the site of DNA damage, resulting in the recruitment of cockayne syndrome type A and type B proteins (CSA and CSB) (ERCC8 and ERCC6)." (PMID 35582447, 2020).
microcephaly (4 papers, 2017 to 2026). A congenital or acquired developmental disorder in which the circumference of the head is smaller than normal for the person's age and sex. "Here, we report a novel mutation in ERCC8 gene in a 16-year-old boy who suffers from poor weight gain, short stature, microcephaly, intellectual disability, and photosensitivity." (PMID 28848724, 2017). "Mutations in ERCC8 have been associated with defects in the transcription-coupled nucleotide excision repair (TC-NER) leading to CSA, characterized mainly by growth failure, microcephaly and developmental delay." (PMID 36231052, 2022).
UV-sensitive syndrome (4 papers, 2017 to 2025). UV-sensitive syndrome is a condition that is characterized by sensitivity to the ultraviolet (UV) rays in sunlight. "In addition to CS, variants of ERCC8 has also been linked to UV-sensitive syndrome (UVSS), which is restricted only to photosensitivity and pigmentation and absence of any neurological anomalies." (PMID 36231052, 2022). "Indeed, variants in ERCC6 and ERCC8 genes have been also associated with the UV sensitive syndrome (UVSS), a milder form clinically characterized by mild cutaneous symptoms." (PMID 35248096, 2022). "Homozygous ERCC6/ERCC8 mutations also result in UV-sensitive syndrome." (PMID 29057985, 2017).
progeria (3 papers, 2014 to 2026). "Cockayne syndrome (CS) is a rare hereditary progeria that is compromised in handling such situations, caused by mutations in either the ERCC6/CSB gene or the ERCC8/CSA gene." (PMID 39704188, 2025).
gastric cancer (2 papers, 2017 to 2021). A primary or metastatic malignant neoplasm involving the stomach. "Population-based epidemiologic studies have shown that ERCC6 and ERCC8 polymorphisms have a significant impact on the risk of some human malignancies, including gastric cancer." (PMID 28562347, 2017). "This study aimed to evaluate the interactions between single nucleotide polymorphisms of ERCC6 (rs1917799) and ERCC8 (rs158572 and rs158916) in gastric cancer and its precancerous diseases." (PMID 28562347, 2017). "In conclusion, ERCC6 rs1917799, ERCC8 rs158572 and rs158916 demonstrated pairwise epistatic interactions to associate with chronic atrophic gastritis and gastric cancer risk." (PMID 28562347, 2017). "ERCC6 rs1917799 also showed a significant interaction with ERCC8 rs158916 to reduce gastric cancer risk." (PMID 28562347, 2017). "In situ ERCC6 and ERCC8 protein expression were detected by immunohistochemistry in 109 chronic superficial gastritis, 109 chronic atrophic gastritis and 109 gastric cancer cases." (PMID 28562347, 2017). "Our results demonstrated pairwise epistatic interactions between ERCC6 and ERCC8 SNPs that ERCC6 rs1917799-ERCC8 rs158572 combination was associated with decreased risk of chronic atrophic gastritis and increased risk of gastric cancer." (PMID 28562347, 2017). "Correlation between ERCC6/ERCC8 expression and survival in gastric cancer." (PMID 34316408, 2021). "Pearson’s correlation analysis using data from 37 gastric cancer cell lines showed that ERCC6 mRNA expression was significantly correlated with JAK2 protein expression (r = −0.345; P = 0.037), and ERCC8 mRNA expression was associated with Src protein expression (r = −0.417; P = 0.010)." (PMID 34316408, 2021). "Through analyzing the expression data of 37 gastric cancer cell lines from CCLE, we figured out that ERCC6 mRNA expression was correlated with JAK2 protein expression, and that ERCC8 mRNA expression was related to Src protein expression." (PMID 34316408, 2021). "However, the relationship between individual and joint expressions of ERCC6/ERCC8 and clinicopathological parameters as well as prognosis of gastric cancer (GC) still remains unclear." (PMID 34316408, 2021). "The expressions of ERCC6, ERCC8 and ERCC6-ERCC8 combination have similarities that higher positivity was observed in chronic superficial gastritis compared with chronic atrophic gastritis and gastric cancer." (PMID 28562347, 2017). "In our previous study, we systematically analyzed the association of 43 SNPs of ten key NER pathway genes including ERCC6, ERCC8 with survival of gastric cancer (GC) patients, and found that ERCC6 SNP could predict GC prognosis." (PMID 28562347, 2017).
skin cancer (2 papers, 2017 to 2022). "Recently, it was reported that ERCC6 and ERCC8 deficient mice were more susceptible to both UV- and chemically-induced skin cancer." (PMID 28562347, 2017).